INS (insulin)
Diseases named in the same sentence as INS in open-access papers (continued):
Sharing a sentence is not in itself a finding about the gene and the disease.
Hepatic steatosis (continued). "Improved insulin signaling through the regulation of IRS-1 was also identified as a mechanism of action whereby Afriplex GRTTM ameliorated hepatic steatosis." (PMID 38630788, 2024). "The research that informs international guidelines highlights the specific benefits of the Mediterranean diet (MedDiet) for improving hepatic steatosis and insulin sensitivity." (PMID 38717691, 2024). "In animal models, the administration of FGF19 and FGF21 improves insulin sensitivity, lipid levels, and liver steatosis while ameliorating body weight and fat mass." (PMID 38891828, 2024). "This was determined by evaluating hepatic steatosis severity and the phosphorylation levels of key proteins in the hepatic insulin signaling pathway (PI3K/AKT/GSK3β)." (PMID 38599845, 2024). "The research revealed that KA has the ability to suppress hepatic DNL, lower blood lipid levels, prevent lipid accumulation in the liver and WAT, enhance insulin sensitivity, and reduce hepatic steatosis." (PMID 38655315, 2024). "Previous research reported that THE improves fatty liver-related pathological processes, such as lipid deposition, insulin resistance, inflammatory, and fibrosis." (PMID 39335905, 2024). "The TyG index was found to be positively correlated with the risk of GDM after adjusting for parity, age, hepatic steatosis, pre-pregnancy BMI, AST, HDL-C, GGT, LDL-C, insulin, ALT, and TC (OR: 13.204, 95%CI: 2.547–68.446, p = 0.00211)." (PMID 38414896, 2024). "Previous research showed that supplementation with Lovaza, an n-3 drug, enhances lipid metabolism, reduces hepatic steatosis, downregulates lipogenic gene expression, stimulates beta-oxidation, and improves insulin sensitivity in murine models." (PMID 39770889, 2024). "Flavonoids positively intervene in various forms of liver steatosis, such as by regulating lipid metabolism, insulin resistance, inflammation, and oxidative stress." (PMID 39594428, 2024). "Because hepatic lipid deposition is a major feature of insulin resistance in the liver, we investigated hepatic steatosis at the macroscopic level, showing that HF-fed mice developed hepatomegaly and a yellow-orange liver coloration." (PMID 39060446, 2024). "Secondary bile acids have been reported to ameliorate hepatic steatosis and augment insulin sensitivity." (PMID 38409604, 2024). "Silencing the HNF4A gene in mice improved glucose tolerance and insulin sensitivity, with beneficial outcomes for liver steatosis and fibrosis." (PMID 39459592, 2024). "By increasing peroxisome proliferator-activated receptors and adiponectin levels, exercise has the potential to ameliorate hepatic steatosis, leading to improved insulin resistance and enhanced lipolysis." (PMID 38595644, 2024). "The relationship between dietary fiber and hepatic steatosis is intricate, potentially involving various mechanisms such as insulin resistance, hepatic lipid metabolism, and changes in gut microbiota." (PMID 38730369, 2024). "In this study, mice fed sand TMPs showed not only improved insulin sensitivity but also reduced HFD-induced hepatic steatosis." (PMID 39408297, 2024). "The univariate analysis results indicate that pre-pregnancy BMI, TG, grade of hepatic steatosis, insulin, GGT, FPG, TyG index, and ALT were positively correlated with the occurrence of GDM." (PMID 38414896, 2024). "By improving insulin resistance in adipocytes, the flow of FFAs and glycerol to the liver was limited, preventing the development of hepatic steatosis in ChATCre mice that lack cholinergic innervation to the liver during HFD feeding." (PMID 39436946, 2024). "NAFLD induced by hepatic steatosis is commonly accompanied by decreased insulin sensitivity and glucose tolerance, which further develop from simple steatosis to NASH." (PMID 39426289, 2024). "Generally, abnormalities in mitochondrial function and increased reactive oxygen species affect fatty liver disease through insulin sensitivity." (PMID 39599914, 2024).
Hepatic steatosis (continued). "In animal studies, lycopene supplementation reduced inflammation, improved insulin sensitivity, and reduced fatty liver disease in rodents fed a high-fat diet." (PMID 39519540, 2024). "For example, CHOP depletion in β cells provides a therapeutic strategy to alleviate ER stress and dysregulated insulin secretion and consequent fatty liver disease." (PMID 38673953, 2024). "Liver steatosis is believed to significantly contribute to liver insulin resistance, leading to elevated gluconeogenesis and reduced glycogen synthesis, subsequently leading to disturbed glucose homeostasis." (PMID 39272460, 2024). "In obese mammals, the liver often exhibits impaired responsiveness to insulin, leading to hepatic insulin resistance and excessive conversion of glucose into fat, which in turn results in fatty liver disease and liver damage." (PMID 39138413, 2024). "Continuously elevated insulin concentrations, as seen with a high sugar consumption, encourage the development of adipose tissue and fatty liver disease." (PMID 38474749, 2024). "PKCε has also shown to facilitate hepatic steatosis and impairment of hepatic insulin signaling, thus, promoting insulin resistance which is a major factor in liver disease and development of HCC in patients with chronic HCV infection." (PMID 36782184, 2023). "Compared to WT mice on the HFD, Alb−/− exhibited lower plasma FFA levels, lower blood glucose levels during glucose tolerance and insulin tolerance tests, and lower hepatic steatosis and inflammation." (PMID 37432201, 2023). "In ob/ob mice, liver-specific silencing of ChREBP can prevent hepatic steatosis and improve peripheral insulin sensitivity, and its mechanism involves the reduction of hepatic DNL." (PMID 38089874, 2023). "Aging FOXA3 gene deficient mice increased white adipose browning and thermogenesis, reduced adipose tissue expansion, improved hepatic steatosis and insulin sensitivity, and extended lifespan." (PMID 36798663, 2023). "Chronic high fat, high fructose diet-feeding induces hepatic steatosis and reduces whole-body insulin sensitivity in ovariectomized rats." (PMID 37509710, 2023). "Hepatic MANF overexpression improved adipose inflammation, insulin sensitivity and hepatic steatosis in HFD-fed mice." (PMID 37928262, 2023). "The high expression of METTL3 and low expression of TYHDF2 in the liver of T2D increased the mRNA stability of Fasn, Acc1, and Srebp-1c, leading to hepatic steatosis and further reducing organ insulin sensitivity." (PMID 37484964, 2023). "Hepatic steatosis, glucose tolerance, insulin and glucagon resistance, and hepatic transcriptomics were investigated at the end of the study period and treatment groups were compared with mice undergoing sham surgery only (Sham‐Ad lib)." (PMID 37208943, 2023). "In this study, loganin treatment inhibited HFD- and OVX-induced weight gain and fat deposition reduced metabolic abnormalities, such as hepatic steatosis and adipocyte expansion, and increased the plasma levels of insulin and leptin." (PMID 36902181, 2023). "Saroglitazar improves insulin sensitivity and ameliorates hepatic steatosis by decreasing fatty acid influx to the liver and enhancing fatty acid oxidation." (PMID 36650455, 2023). "p300 can acetylate FOXA2, thereby blocking its nuclear rejection and increasing its transcriptional activity, which further led to increased mitochondrial oxidation, hepatic ketogenesis, insulin sensitivity and attenuated hepatic steatosis in db/db mice." (PMID 36798663, 2023). "Studies have shown the importance of EGR1 in maintaining the hepatic insulin response and claimed that the loss of EGR1 in hepatocytes leads to hepatic steatosis, which exacerbates the progression of non-alcoholic liver disease." (PMID 37405258, 2023). "The univariate analysis showed that pre-pregnancy BMI, grade of liver steatosis, TG, ALT, GGT, FPG, insulin, HOMA-IR, and TG/HDL-C ratio were positively associated with incident GDM." (PMID 37576966, 2023).
Hepatic steatosis (continued). "A number of studies revealed that FGF21 also had properties that promote glucose uptake in adipocytes, increase insulin secretion, improve insulin sensitivity, enhance fatty acid oxidation, and attenuate hepatic steatosis." (PMID 37180779, 2023). "The first hit is made by insulin resistance and lipid accumulation, resulting in simple hepatic steatosis." (PMID 36658156, 2023). "In vivo, both olive-oil-enriched (HFD + OO) and fish-oil-enriched high-fat diets (HFD + FO) reduced hepatic steatosis and improved insulin sensitivity in obese mice." (PMID 37513618, 2023). "This candesartan-mediated enhancement of insulin sensitivity resulted in improved hepatic function, reduced hepatic steatosis and hyperlipidemia, and reduced adipocyte inflammation in HFD-fed mice." (PMID 37121975, 2023). "With the decrease of FFA in plasma, hepatic steatosis was also reduced, and insulin sensitivity was improved." (PMID 36979342, 2023). "Prenatal exposure to the oligofructose prebiotic ameliorated glucose tolerance, insulin sensitivity, and hepatic steatosis in offspring of dams consuming a high fat/sucrose diet." (PMID 35848617, 2023). "Conversely, other studies suggest that Kupffer cells modulate hepatic steatosis by secreting anti-inflammatory cytokines that stimulate insulin signaling in the hepatocytes." (PMID 37242206, 2023). "ADe significantly controlled body weight; alleviated hepatic steatosis and adipocyte hypertrophy; reduced aspartate aminotransferase, total cholesterol, insulin, and resistin; and increased adiponectin levels in HFD-fed mice serum." (PMID 36839230, 2023). "ACC inhibitors can reduce hepatic steatosis, improve insulin sensitivity, and regulate dyslipidemia, making them one of the most promising therapeutic targets for MASLD." (PMID 38089874, 2023). "At the same time, FA can inhibit liver fibrosis, inhibit liver steatosis and reduce lipid toxicity, improve insulin resistance in the liver and exert the effect of anti-liver cancer." (PMID 37324465, 2023). "The findings imply the impact of genes involved in BER on NAFLD and fatty liver-related insulin sensitivity." (PMID 37511066, 2023). "Even more so, feeding EPA and DHA enriched diet prevents the development of severe hepatic steatosis and increases adiponectin levels and insulin sensitivity in obese mice." (PMID 36994095, 2023). "Liver steatosis, inflammation, impaired insulin signaling pathway and endoplasmic reticulum stress are similar comparing animals that consumed HFHS once-a-week with those that continuously consumed HFHS, though weekly-fed animals did not gain as much weight." (PMID 36810903, 2023). "Increased palmitoyl-CoA availability increases de novo ceramide synthesis and sphingomyelin hydrolysis in peripheral tissues of obese insulin-resistant animals with hepatic steatosis." (PMID 38274826, 2023). "In rodent models, RPTOR deletion in adipocytes diminishes white adipose tissue (WAT) and promotes lipolysis and gradual lipodystophy with a parallel lipid accumulation in the liver, developing hepatic steatosis, hepatomegaly, and insulin resistance." (PMID 36986146, 2023). "AMPK activation reduces hepatic steatosis and enhances insulin sensitivity, which in turn inhibits gluconeogenesis." (PMID 37759824, 2023). "The activation of the post-receptor signaling cascade induced by GLP-1 and GLP-1 receptor agonists and the consequent modulation of insulin signaling pathway would reduce storage of hepatocyte triglyceride and consequently improve hepatic steatosis." (PMID 36675217, 2023). "CD36 deletion in hepatocytes reduced HFD-induced hepatic steatosis, decreased hepatic fatty acid uptake, and improved whole-body insulin sensitivity." (PMID 37764494, 2023). "Studies have shown that the SCGN-insulin interaction can stabilize insulin, enhance the hypoglycemic activity of insulin in vivo, and reduce hepatic steatosis and cholesterol metabolism disorders." (PMID 37033223, 2023).
Hepatic steatosis (continued). "The Mediterranean Diet improves hepatic steatosis, and insulin sensitivity in individuals with nonalcoholic fatty liver disease." (PMID 37049618, 2023). "Evaluation of the supplementation with 250 and 500 mg/day of DHA or placebo in Italian children who had liver ultrasonography and biopsy consistent with NAFLD exhibited lower hepatic steatosis and TG, and higher insulin sensitivity with both DHA dosages." (PMID 38004223, 2023). "Animals fed the CAF diet showed significantly increased body weight compared to those fed NC, accompanied by abnormal changes in their systemic insulin and triglycerides, elevation of hepatic triglyceride and hepatic steatosis." (PMID 38201945, 2023). "Of special interest is the hepatokine FGF21 which protects from hepatic steatosis and improves insulin sensitivity in mice and humans when administrated." (PMID 36923222, 2023). "Randomized controlled crossover experiments have illustrated the advantages of MD over LFD in improving insulin sensitivity, metabolic parameters and hepatic steatosis." (PMID 37899839, 2023). "Higher hepatic IR and lower whole-body insulin sensitivity were observed with increasing hepatic steatosis severity as shown by HOMA-i and the Matsuda index, respectively." (PMID 38068910, 2023). "Paeoniflorin significantly decreased serum insulin and glucagon levels, improved insulin sensitivity and serum lipid profile, and alleviated hepatic steatosis in fructose-fed rats." (PMID 38029230, 2023). "In an HFD-induced metabolic disorder model, replacing 20% HFD with UFAs (fish oil or olive oil) improved the biochemical parameters, alleviated hepatic steatosis, and improved insulin sensitivity in obese mice." (PMID 37513618, 2023). "Prior research, predominantly conducted in males, has showcased that the activation of the CAR receptor through pharmacological agonists can ameliorate glucose and insulin tolerance and alleviate hepatic steatosis in animals afflicted with metabolic disorders." (PMID 37759441, 2023). "We observed a positive association between the muscle quality index (MQI) and the disposition index—as proxies of muscle strength and insulin sensitivity, respectively—after adjustment for menopause, body fat percentage, and the presence of hepatic steatosis." (PMID 36831008, 2023). "In patients with hepatic steatosis and lipodystrophy, leptin treatment improves insulin-stimulated hepatic and peripheral glucose metabolism, suggesting potential therapeutic approaches." (PMID 38137501, 2023). "It has been shown that ApoE KO male mice at 12 months of age have increased serum levels of TAG, glucose, and insulin in addition to hepatic steatosis and increased plasma levels of liver enzymes, demonstrating liver damage." (PMID 37372993, 2023). "Insulin plays a central role in regulation of lipid metabolism, suggesting the dysregulated insulin response in hepatic steatosis groups." (PMID 37568219, 2023). "Of note, we demonstrated systematic improvements on muscle mass, insulin sensitivity, lipid parameters, fat mass, and hepatic steatosis after AAV‐NLS‐PGC1α4 delivery in muscle." (PMID 37584432, 2023). "A previous study showed that hepatic hypomethylation enhances Pparα expression, reduces hepatic steatosis, and increases insulin sensitivity." (PMID 37484964, 2023). "GRP78 mitigates hepatic steatosis by inhibiting insulin- and ER stress-induced genes involved in lipid biosynthesis in obese mice." (PMID 37138269, 2023). "The phenotype of mice with the overexpression of FIAF is interesting and characterized by liver steatosis but there is also a better insulin sensitivity in the liver and other major target tissues." (PMID 37274345, 2023). "Previous studies reported that impaired insulin action is a step preceding the induction of T2D and comorbidities such as abdominal obesity, hyperlipidemia, hepatic steatosis, PCOS, increased blood pressure, and cardiovascular disease." (PMID 37754255, 2023).
Hepatic steatosis (continued). "In this regard, it has been shown that RSV can mitigate hepatic steatosis (lipid deposition), inflammation, and fibrosis and improve insulin sensitivity." (PMID 37764672, 2023). "Liver-specific Pander overexpression leads to hepatic insulin resistance, and increased gluconeogenesis and lipogenesis, resulting in hepatic steatosis onset in mice." (PMID 36923222, 2023). "It is important to note the relatively short treatment period that was used in the present study and the impressive effects that were observed on fasting blood glucose and insulin as well as hepatic steatosis." (PMID 36830621, 2023). "alleviated hepatic steatosis induced by a high-fat diet, attenuated chronic inflammation in the liver, ameliorated insulin sensitivity, and improved the function of the gut barrier." (PMID 37894792, 2023). "Reduced body weight and fat mass;Improved glucose homeostasis and insulin sensitivity;Prevention of liver steatosis, reduction of liver injury." (PMID 37111034, 2023). "Higher levels of respective CD36 are a biomarker of high-fat diet-induced hepatic steatosis, and its reported knockdown improved insulin sensitivity and steatosis owing to observed decrease in FA uptake and TAGs concentration." (PMID 36771233, 2023). "At low levels, it exerts a protective effect on hepatic steatosis due to its insulin-sensitizing effects, suppression of gluconeogenesis, and de novo lipogenesis, as well as its stimulation of FFA beta-oxidation." (PMID 36830859, 2023). "Several animal models have demonstrated that the potent SPT inhibitor myriocin, frequently used to suppress de novo ceramide biosynthesis, improves insulin sensitivity and hepatic steatosis, and protects against atherosclerosis and cardiomyopathy." (PMID 38274826, 2023). "Correspondingly, our previous study has shown that uric acid regulates hepatic steatosis and impairs insulin sensitivity through activating the NLRP3 inflammasome both in vivo and in vitro." (PMID 36814289, 2023). "Several drugs, including thiazolidinediones (peroxisome proliferator-activated receptor gamma (PPARγ) agonists that are insulin sensitizers) are being investigated as therapies to reduce hepatic steatosis, inflammation, and fibrosis." (PMID 36837793, 2023). "Data reported an improvement in anthropometric parameters and body composition, and the subjects reduced liver steatosis, liver enzymes, insulin levels, HOMA, and IL-6." (PMID 38004223, 2023). "In obese, insulin-resistant C57BL/6J mice Xu and colleagues reported that empagliflozin diminished weight gain and reduced deteriorations of insulin sensitivity and hepatic steatosis of ongoing high-fat-diet feeding." (PMID 36525084, 2023). "On the other hand, deletion of the gene encoding SREBP-1c in livers of ob/ob mice, which are insulin resistant, results in an approximate 50% reduction of hepatic triglycerides (TGs), indicating the role of SREBP-1c in the hepatic steatosis in ob/ob mice." (PMID 38137501, 2023). "Hepatic glucose homeostasis influences insulin sensitivity, while peripheral insulin resistance and lipolysis contribute to fat accumulation in the liver (hepatic steatosis)." (PMID 37899468, 2023). "Hepatic steatosis improved even with a short-term (<1 week) ketogenic diet, and a ketogenic diet improved hepatic insulin sensitivity, mitochondrial fluxes, redox state, and hepatic steatosis." (PMID 37892188, 2023). "Stimulating CB1R with specific agonists increases the secretion of insulin, somatostatin, and glucagon; it increases fat storage by stimulating lipoprotein lipase and release of adiponectin, and as a result, hepatic steatosis and IR develop." (PMID 36830844, 2023). "In animal studies, Zn supplementation in rats with diet-induced NAFLD was found to reduce the severity of hepatic steatosis in periportal areas, reduce lipid deposition in hepatocytes, improve glucose metabolism and insulin signalling, and reduce liver damage." (PMID 37571395, 2023).